IL10 (interleukin 10)
Diseases named in the same sentence as IL10 in open-access papers (continued):
Sharing a sentence is not in itself a finding about the gene and the disease.
immune dysfunction (continued). "The immune dysfunction scoring system developed here incorporates plasma G-CSF level, IL-10 level, serum SeMo ratio, and monocyte HLA-DR expression and appears valid and reproducible for predicting 28-day mortality." (PMID 29073262, 2017). "IL-10 has been shown to be beneficial in improving systemic immunity by having anti-inflammatory effects and promoting the repair of immune dysfunction after the invasion of different pathogens." (PMID 28331850, 2017). "In medication-treated groups, only treatment with midazolam clearly decreased the IL-10 expression, indicating that midazolam is able to suppress the hypersecretion of IL-10, reduce immune dysfunction and thereby improve the survival rate in septic mice." (PMID 25780458, 2015). "Monocytes and macrophages produce interleukin (IL)-10, an immunoregulatory cytokine and a potent therapeutic tool for immune disorders." (PMID 25896516, 2015). "Posttraumatically, immune disorder was accompanied by a significant increase of IL-10 and STAT 3 mRNA expression, whereas SOCS 1 mRNA levels decreased after injury." (PMID 24648661, 2014). "Posttraumatically, immune disorder is accompanied by a significant increase of IL-10 and STAT 3 mRNA expression (6 h), whereas SOCS 1 mRNA levels decrease after injury." (PMID 24648661, 2014). "The top canonical pathways were concerned with the role of pattern recognition receptors, production of reactive oxygen species, IL10 signaling and role of macrophages in immune disease, consistent with the known roles of IL-6 family of cytokines." (PMID 21637858, 2011). "Overdosing might induce nephrotoxicity, hepatotoxicity, or immune dysfunction through direct or indirect immunomodulation (e.g., IL-10 suppression)." (PMID 40943845, 2025). "The increases in the proinflammatory cytokines IL-1a, IL-8, IL-17A, IL-12p40, TNF-β, MCP-1, IL-2, and IL-12p70 and the anti-inflammatory cytokines IL-10 and IL-13 observed in AD patients in our study are consistent with prior evidence of immune dysfunction in AD." (PMID 39346576, 2024). "In addition, Treg cells can play an anti-inflammatory role in various immune diseases by secreting anti-inflammatory cytokines, including IL-10, and inhibiting immune cell activity." (PMID 37446006, 2023). "Besides, miR-148 improved the immune dysfunction induced by MI/R through increasing the number of interleukin (IL)-10+ cells and reducing the number of inducible nitric oxide synthase (iNOS)+ cells." (PMID 34517782, 2021). "Interestingly, inflammatory mediators such as CRP, TNF-α, IL-1ra, IL-6, IL-8, and IL-10 have been identified to be part of both: age-related diseases and trauma-induced immune dysfunction." (PMID 32258173, 2020). "Besides, CXCL10, CXCL11, and IL-10 also played critical roles in immune disease." (PMID 40458609, 2025). "Therefore, the activation of the α7 nAChRs and, thus, regulating both the HLA-DR expression and IL-10 production may be a way to prevent the immune dysfunction." (PMID 32230846, 2020). "Given the crucial importance of IL-10 in immune dysfunction and the capacity of IL-10 to synergize with inflammatory cytokines to enhance viral replication in HIV-1-positive patients, inhibition of Tat/TLR4-MD2 may represent in the long term an attractive therapeutic strategy." (PMID 25471526, 2014). "Recently, in the context of HIV infection, it has been shown that IL-10 induction leads to changes in DC compartments and suppresses NK killing of immature DCs, thus promoting accumulation of poorly immunogenic APCs, which contribute to the immune dysfunction observed in HIV patients." (PMID 22876184, 2012). "Cytokine profiling showed decreased levels of IL-2, IL-6, IL-10, TNF-α, and IFN-γ, indicating broad-spectrum immune dysfunction." (PMID 40806124, 2025). "Despite higher IL-10 levels in the PRRSV group, pro-inflammatory cytokines remained unchanged, indicating PRRSV-induced immune dysfunction." (PMID 39161459, 2024).
immune dysfunction (continued). "The addition of Wenyang Huazhuo Tuihuang Decoction can reduce the proinflammatory factor IL-32 level and increase the inflammation inhibitory factor IL-10 level in patients with HBV-related ACLF, which has a certain regulatory effect on immune disorders." (PMID 35399641, 2022). "These expanded populations may be functionally equivalent to the IL10-producing B cell populations found to be elevated in PBMC’s from the blood of APDS patients, and which contribute to immune dysfunction in APDS." (PMID 41191641, 2025). "Therefore, this concomitant upregulation of IL10 and pro-inflammatory genes by yeast culture supplementation during the transition period suggests an attenuated inflammatory response, which might be beneficial considering cows experience immune dysfunction during this period." (PMID 36670844, 2023). "The induction of IL-10 was rare, indicating that IL-10 mediated immunomodulation/immune dysfunction was not a feature of this vaccine or of the challenge virus." (PMID 30761215, 2019). "Furthermore, we found that levels of salivary IL-6, IFN-γ, IL-10, IL-17A, and TNF-α in OLP patients were significantly upregulated, likely because of the oral immune disorder." (PMID 28400582, 2017). "Therefore, promoting B10 cells in auto-immune diseases and inhibiting B cell IL-10 production in CLL are promising therapeutic tools, requiring a better comprehension of B cell IL-10 production regulation." (PMID 28072868, 2017). "Recently, IL-10 producing regulatory CD19(+) B cells has been intensively studied in abrogating immune-pathologies and modulatory IL-10 has been beneficial for prevention of auto-immune diseases." (PMID 23724100, 2013). "Previous studies suggested that CD is a T helper 1-mediated immune disease characterized by increased cytokine levels of IFN-γ, TNF-α, and IL-12, whereas UC is a T helper 2-mediated immune disease characterized by increased cytokine levels of IL-6 and/or reduced IL-10." (PMID 28683149, 2017). "The immune dysfunction is not probably due to impaired T-cell function, since neither CD4+ T-cell dependent IFNγ producing cell number nor IL10 producing regulatory T-cells resulted different outcomes in response to PMA-Ionomycin and PHA-LPS stimulation, respectively." (PMID 28170444, 2017). "Unlike usual immunotherapies for immune diseases, venom therapy not only induces a rapid shift in cytokine expression from Th2 (IL-4) to Th1 (IFN-γ) cytokines, but also leads to increased production of immunosuppressive cytokine IL-10 during the initial phase of the treatment." (PMID 26825274, 2016).
infectious disease (110 papers, 2006 to 2026). A disorder directly resulting from the presence and activity of a microbial, viral, or parasitic agent in humans. "This cytokine play important roles as a regulatory cytokine and, in the context of an infectious disease, as IL-10 helps to prevent tissue damage caused by the immune response." (PMID 40391210, 2025). "The IL10 rs1800872 polymorphism is linked to an increase in the severity of autoimmune and infectious diseases and regulates the transcription and production of IL10." (PMID 36882862, 2023). "Genetic variations in the IL-10 gene promoter influence the levels of IL-10 production and are associated with the outcome of infectious diseases and inflammatory disorder." (PMID 35860267, 2022). "In the context of infectious diseases, it is believed that the host uses IL-10 to control over-exuberant immune responses to pathogenic microorganisms in order to limit tissue damage." (PMID 23818855, 2013). "On one hand, IL-10 plays a crucial role in the resolution of inflammation and as such reduces the risk of immunopathology when organisms face an infectious disease." (PMID 20886083, 2010). "IL-10 dysregulation is implicated in different infectious diseases." (PMID 38251210, 2024). "A study of the Dubbo Infectious Outcomes Study (DIOS) post-infective fatigue syndrome (PIFS) cohort found that the interleukin-10 -592C/A polymorphisms were significantly associated with illness severity, cytokine protein levels and the duration of illness in those with an infectious disease." (PMID 30567628, 2019). "IL-10 can protect tissues from colateral damage caused by excessive inflammation, but in infectious diseases, where an inflammatory response is required to prevent parasite proliferation, IL-10 may prevent an ideal response." (PMID 26814478, 2016). "As an alternative explanation of the association between the IL-10 gene variants and muscle strength, pro-inflammatory IL-10 gene variants might yield a better resistance to infectious diseases and thereby a better resistance to muscle wasting due to disease." (PMID 25040424, 2014). "However, loss of IL-10 driven immune modulation has been shown to cause severe and sometimes lethal inflammatory responses in different infectious disease models." (PMID 23818855, 2013). "The effect of the IL-10 -1082 G/A polymorphism on the incidence and outcome from infectious disease has been contradictory and may be organism-specific or vary according to ethnicity." (PMID 16611358, 2006). "The enrichment of pathogenic IL10RA variants across East Asia and characteristic endemic presence of infectious disease with known functional link to the IL-10 signaling pathway led us to hypothesize that these variants mediate environment-specific increased fitness in heterozygous carriers." (PMID 36370291, 2023). "Therefore, our aim was to investigate the IL10 functional variants that can modulate or alter serum IL10 levels, which may leads to either increased or decreased risk for infectious disease on whole, VL in particular." (PMID 25941808, 2015). "Future studies are needed to elucidate whether variants of the IL-10 gene determine handgrip strength through their role in the repair of skeletal muscle tissue directly or indirectly through their role in the defence against infectious diseases." (PMID 25040424, 2014). "This study suggests HEBP’s potential in fish nutrition for use as a feed additive and in improving fish health management against infectious diseases by intensifying the immune responses of IL-4 and IL-10." (PMID 39185043, 2024). "Strategies to enhance IL-10 production or delivery, or to mimic its effects, are being explored as potential interventions in infectious diseases such as Streptococcus pneumoniae infection." (PMID 38251210, 2024). "IL-10 is a potent anti-inflammatory cytokine that plays a crucial role in modulating immune responses during infectious diseases." (PMID 38251210, 2024).
infectious disease (continued). "Much of our understanding regarding the role of IL-10 in infectious disease originates from observations in the murine model." (PMID 38465263, 2024). "IL-10 and IL-4 are common anti-inflammatory cytokines, playing a crucial part in mediating humoral immune response, infectious disease, etc.." (PMID 38998101, 2024). "In some cases, the dysregulation of IL-10 in infectious diseases allows pathogens to escape the host’s immune responses, causing persistent infections." (PMID 38251210, 2024). "IL-10 has shown potential in the treatment of infectious diseases due to its ability to regulate immune responses and mitigate excessive inflammation." (PMID 38251210, 2024). "In the context of infectious diseases, IL-10 helps to prevent immunopathology and limit tissue damage caused by the immune response." (PMID 38251210, 2024). "The increased susceptibility of CKO mice to T. cruzi infection warranted further investigation, especially considering the involvement of Blimp-1 in suppressing the immune response in infectious diseases through IL-10 production." (PMID 37908369, 2023). "The IL-10-producing cell type depends on the inducing stimulus, e.g., Th1, Th17 cells, and macrophages represent an important source of IL-10 in infectious diseases." (PMID 36835413, 2023). "The anti-inflammatory properties of IL-10 has been shown to limit the development of tissue pathology in a range of infectious diseases." (PMID 36888692, 2023). "Overall, HLA-G expression is upregulated in infectious diseases in response to changes in the cytokine microenvironment that is mainly related to increased levels of IL-10 and class I interferons." (PMID 35204759, 2022). "IL-6 and IL-10 are two essential components of inflammatory response in almost all infectious diseases released by a range of different cells." (PMID 34088317, 2021). "The IL-10 rs1800872 is related to increased intensity of autoimmune and infectious diseases which can control the transcription and expression of IL-10." (PMID 33766078, 2021). "Interleukin (IL)-35-secreting B (IL-35+B) cells are critical regulators in autoimmune and infectious diseases and exert suppressive functions in parallel with IL-10-producing B (B10) cells." (PMID 33912178, 2021). "Naïve and memory B10 cells are thought to have different functions in autoimmune and infectious diseases in humans, and their IL-10 production depends on specific activation signals in a particular immunological environment." (PMID 33750870, 2021). "IL-10 is an anti-inflammatory cytokine that plays a significant role in the modulation of the immune response in many pathological conditions, including infectious diseases." (PMID 33072115, 2020). "In some instances, response to infectious diseases drives the development of IL-10-producing Breg cells in both mice and humans." (PMID 32973780, 2020). "In infectious diseases such as with viruses, enhanced production of IL-10-producing transitional B cells positively correlates with the viral load." (PMID 32973780, 2020). "The most well-studied of these subsets are IL-10-producing Th1 (Tr1) cells that have been identified in many infectious diseases, including visceral leishmaniasis, tuberculosis, and human immunodeficiency virus." (PMID 30809232, 2019). "The rs1800872 polymorphism that is located at the 5′-flanking region of IL-10 promoter is related to increased intensity of autoimmune and infectious diseases and control the transcription and expression of IL-10." (PMID 31196204, 2019). "The finding can be in consistent with the assumption that high levels of IL-10 can help in preventing post infectious diseases tissue damage." (PMID 31363402, 2019). "Another basic helix-loop-helix family member Twist-1 also regulates IL-10 production, although little is currently known about its role in infectious diseases settings." (PMID 30809232, 2019).
infectious disease (continued). "Levels of IL-10 control the balance between inflammatory and humoral responses, and IL-10 therefore plays an important role in the development of infectious disease." (PMID 25750641, 2015). "The cytokine IL-10 has a major impact on the regulation of inflammation and the progression of a multitude of infectious diseases." (PMID 23825956, 2013). "Whereas the regulatory role of IL-10 in vitro and in animal models is well documented, the role of this cytokine in clinical situations, particularly in infectious diseases, remains the subject of investigation." (PMID 23303806, 2013). "In a number of infectious disease models, several cell types, including T cell subsets, B cells, neutrophils, macrophages and some DC subsets have been shown to be able to produce IL-10." (PMID 23818855, 2013). "Anti-inflammatory mediators, especially IL-10 has been shown to play greater roles in counterbalancing the proinflammatory response in various infectious diseases." (PMID 22529524, 2012). "Recently more emphasize is on regulatory T cells and IL-10 secreting Th1 cells as the sources of IL-10 in pathophisiology of several chronic inflammatory and infectious diseases." (PMID 23109946, 2012). "In rodent models of infectious disease, neutralizing IL-10 leads to uncontrolled pro-inflammatory responses and thus increased immunopathological virulence of many parasites." (PMID 18447949, 2008). "IL-10 is crucial for developing strategies to enhance host defense and combat infectious diseases." (PMID 38251210, 2024). "IL-10 plays an important immune regulatory role including activation of anti-inflammatory genes that are important for limiting immune-mediated pathology in many infectious and non-infectious diseases." (PMID 38922041, 2024). "Indeed, ample evidence exists that IL-10 is immunoregulatory in a wide variety of infectious diseases in the development of protective response and inflammation." (PMID 36888692, 2023). "Many studies have shown that IL-6 and IL-10 are related to infectious disease." (PMID 35432366, 2022). "This should be addressed in future studies which should also elucidate whether impaired regulatory IL-10 STAT3 signaling can be a marker of developing severe reactions to infectious diseases." (PMID 35039055, 2022). "Collectively, the MIF and IL-10 dyad could be considered as a potential novel molecular Yin-Yang in infectious disease progression." (PMID 35464430, 2022). "Regulatory B cells (Bregs), newly identified regulatory cells, exert immunoregulatory roles in the course of infectious diseases, autoimmune diseases, and cancer by secreting interleukin (IL)-10, transforming growth factor-β1 (TGF-β1), IL-35, and other inhibitory cytokines." (PMID 33912178, 2021). "The anti-inflammatory cytokine IL-10 is a two faced cytokine in human infectious diseases." (PMID 34589087, 2021). "Sustained high levels of IL-10, and in particular sustained high IL-10/TNF ratio have been demonstrated to be associated with high mortality in meningococcal sepsis as well as in other infectious diseases." (PMID 28261486, 2017). "IL10 may be affected by ancient positive selection in Africa and may now affect differences in these infectious diseases through the T cell receptor signaling pathway." (PMID 28445522, 2017). "Recent results indicate that increased activity of Tregs and regulatory cytokines such as IL-10 may contribute to pathogen persistence by modulating the host immune response in infectious diseases such as TB." (PMID 26248316, 2015). "Studies show that, for some infectious diseases, an increase in IL-10 potentially acts to decrease the deleterious effects of inflammation derived from Th1 cytokines without affecting the clearance of infectious agents, such as Listeria monocytogenes, Trypanosoma cruzi, and influenza virus." (PMID 26495323, 2015). "Secondly, infectious diseases might have interfered with our measurements of IL-10 cytokine production capacity." (PMID 25040424, 2014).